CCND2 (cyclin D2)
Diseases named in the same sentence as CCND2 in open-access papers (continued):
Sharing a sentence is not in itself a finding about the gene and the disease.
cancer (continued). "Cyclin D2 gene promoter is hypermethylated in 12% of GCTs, a number that is consistent with previous findings in other cancers." (PMID 15574200, 2004). "Additionally, upon analyzing the transcriptional changes that occur in these cells after stimulation, we observed a downregulation of several oncogenes and cancer-associated genes, including IL6, MMP2, and CCND2." (PMID 40043049, 2025). "In addition, CCND2 expression was found to increase during cell growth arrest, suggesting its suppressing role in cancer development." (PMID 39507529, 2024). "Examination of DES cluster 5 for expression of Wnt signaling targets, however, indicated that relative to other DES clusters, the DES cancer cells had among the lowest expression of Wnt ligands, receptors, and target genes including Wnt7a, Ccnd2, Axin2, and Myc." (PMID 37856394, 2023). "PRDX6 may promote the occurrence and development of ICC by regulating Wnt7a/Mmp7 in cancer cells and Wnt7b/Ccnd2 in macrophages." (PMID 36209344, 2022). "Interestingly, PTCH1 shows the highest mutation rate in 7% (127/1867; 7%) of cancers, followed by PDGFRA (89/1867; 5%), ABL1 (68/1867; 4%), FOSB (56/1,678, 3%), ALDH1A1 and CCND2 (48/1,678; 2.9%), (55/1867; 2.9%)." (PMID 36704357, 2022). "The effects of resveratrol on the expression of several cancer-related genes, such as CCND-2, p16, RASSF-1α, and cancer-promoting prostaglandin E2 (PGE2), were investigated in a randomized placebo-controlled clinical research in women with a high risk of breast cancer." (PMID 35956766, 2022). "CCND2 is ubiquitously involved in cancer cell proliferation." (PMID 35306579, 2022). "Both CCND1 and CCND2 have been previously reported as deregulated in many cancers." (PMID 35879975, 2022). "Since CCND2 is an important cyclin protein in cancer cells, CAPRIN1 may promote cell proliferation by regulating the cell cycle through binding to CCND2 to induce its expression in NPC." (PMID 36515758, 2022). "As a member of the cyclin family CCND2 has been shown to confer drug resistance in cancer." (PMID 34944554, 2021). "CCND1 and CCND2 belong to the D‐type cyclins and are usually considered promoters of human cancer." (PMID 33473276, 2021). "Collectively, these data suggest that the molecular events regulated by CCND2 AS1 may vary depending on the cancer type." (PMID 32607313, 2020). "However, several studies reported that cyclin D2 plays distinct roles in cell cycle regulation and cancer progression." (PMID 32893977, 2020). "We next investigated whether anti-cancer CCND2 and IRF5 are binding partners of FBXL8, with a view to providing explanations on how their interactions might impact BRCA progression." (PMID 32784654, 2020). "Notably, among the predicted list of FBXL8-binding factors, two cancer suppressors, Cyclin D2 (CCND2) and Interferon Regulatory Factor 5 (IRF5), emerged prominently as potential interaction partners of FBXL8." (PMID 32784654, 2020). "CCND2, a key cell cycle regulator, has been reported to be an oncogene in human cancers." (PMID 33005182, 2020). "The correlation between PICOT and CCND2 could be specific to cancer, reflecting abnormal regulation of the transformed cells, or could be universal and reflect basic cellular control mechanisms." (PMID 31527584, 2019). "In addition, this is the first systematic review to address the prognostic role of CCND2/3 in multiple human malignant neoplasms." (PMID 30950241, 2019). "Since elevated expression levels of PICOT were reported in several different tumors and correlated in the current studies with decreased transcription and translation of the CCND2 gene, we tested whether this opposite correlation exists in human cancers." (PMID 31527584, 2019). "Taken together, CCND2/3 could be the promising biomarkers for predicting the prognosis of patients with malignant neoplasms." (PMID 30950241, 2019). "Our results indicated CCND2/3 played an oncogenic role in all cancer patients." (PMID 30950241, 2019).
cancer (continued). "The impact of miR-193a-mediated interruption of the caprin-1/G3BP-1/c-MYC/Cyclin D2 complex could be a potential target for anti-cancer therapeutic applications." (PMID 28211508, 2017). "This upregulation of miR-141-3p and/or miR-200a-3p may have effects on several cancer-related target genes that have been previously associated with these two miRNAs, including E2F3, GLS, CCND2, PTEN, CCNG1, CDC25B, and ZFPM2." (PMID 28288173, 2017). "In addition, we further showed that increase in miR-329 expression was associated with a decrease in oncogene cyclin D1, cyclin D2, and an increase in p57 and p21. cyclin D1 and cyclin D2 are well-established oncogenes in many different cancers." (PMID 26909600, 2016). "These facts indicate that cyclin D2 might act as a tumour suppressor gene in a cancer-type dependent manner." (PMID 26703571, 2015). "CCND1 and CCND2 are well-established oncogenes in many different cancers." (PMID 26325180, 2015). "Up-regulation of c-Myc and CCND2 has been found in several types of cancer and our data is consistent with the previous studies reporting that the up-regulation of c-Myc and CCND2 may contribute to malignant potentials of ES." (PMID 26393798, 2015). "Moreover, a low abundance of cyclin D2 has been observed in certain carcinoma cell lines, such as MCF7; under certain conditions, the loss of a specific cyclin can be compensated by the presence of others." (PMID 25669982, 2015). "Interestingly, it has been reported that miR-29s target CCND2 in various cancer types and E2F1 in OS." (PMID 25174983, 2014). "Moreover, this is accompanied by CCND2 overexpression and by very high levels of nuclear β-catenin which also strongly correlated to cancer invasivity." (PMID 25174983, 2014). "Functionally, CCND2 plays different roles in different cancer types." (PMID 24980822, 2014). "Cyclin D2/CCND2 has been identified in several cancers as a proto-oncogene." (PMID 22303414, 2011). "CCND2 hypermethylation appears to be common in many cancers." (PMID 21577262, 2011). "The identification of Ccnd2 as a direct target of Elf5 is a novel finding and has implications for the proliferative decisions of mammary epithelial cells during normal development as well as in cancer." (PMID 20831799, 2010). "Furthermore, the differences in methylation status of RASSF1A and CCND2 between the ER-positive and ER-negative groups can be recognized in early stages of cancer, such as the T1c or N0 stages." (PMID 18485221, 2008). "Although their abnormal expression has been linked to cancer development and progression in a number of tissues, the expression of cyclin D2 and D3 proteins in colon cancer has not yet been characterised." (PMID 16012517, 2005). "The reason for this discrepant finding between normal and cancer tissues may be related to the fact that cyclin D2 is a direct target of Myc in which its expression is further controlled by β-catenin." (PMID 12771922, 2003). "Moreover, our results indicate that expression of the CCND2 gene changes notably after entering the critical state, which may facilitate cell cycle progression in cancer cells." (PMID 40729372, 2025). "Hence, we strongly assume that the downregulation of CCND2 might be due to the aberrant overexpression of hsa-mir-15b/mir-16-2 in malignant tumors." (PMID 35845108, 2022). "Interestingly, the expression levels of four genes (PDGFB, CCND2, CTF1, IL7R) identified in the current study were strongly associated with STAT3 activation, clinical outcome of LUAD patients and drugs sensitivity across cancer cell lines in GDSC." (PMID 34301211, 2021). "Therefore, the present results imply that 12p gains may be indispensable for the development of ECs because 12p includes various genes associated with cancer (e.g., DPPA3, GDF3, KRAS, or CCND2)." (PMID 32999426, 2020). "Thus, knockdown of ADK-L-decreased CCND2 expression may affect CCND2-related actions on cell cycle regulation, cancer cell growth inhibition, and migration ability." (PMID 31921385, 2019).
cancer (continued). "This could lead to bias in the effectiveness of CCND2/3 as a prognostic factor in cancer patients." (PMID 30950241, 2019). "It appears, therefore, that downregulation of CCND2 is required for cell cycle progression and replication of certain cell types, and that overexpression of PICOT can lead to excessive downregulation of CCND2 expression, which might promote the cell growth in several types of human cancers." (PMID 31527584, 2019). "Ultimately, the blockade of c-Myc mRNA transport by the tylophorine-mediated sequester of the caprin-1, G3BP1, c-Myc mRNA, and cyclin D2 mRNA-containing RNP complex may contribute significantly to the anti-cancer effects elicited by tylophorine in conjunction with the accumulation of c-Jun." (PMID 25669982, 2015). "This study also explored the prognostic impact of CCND2 and KLF4 expression on various cancer types." (PMID 40487928, 2025). "We also observed re-expression of CCND2, CD82 and IGF1R in three out of four models, which was already described after azacytidine treatment in several cancers." (PMID 36765607, 2023). "We chose CCND1 as a positive control, considering the substantial evidence supporting its role in cancer and the greater depth of CCND1 functional characterization compared with CCND2 and CCND3." (PMID 37081792, 2023). "Cancer cell subcluster 2 also expressed high levels of cell proliferation markers (TOP2A and CCND2) and a goblet cell marker (CLCA1)." (PMID 36690709, 2023). "For ERRFI1, RTN4, PHF7, SPRY4, CCND2, and RPL19, H3K36me3 and H3K79me2 enriched higher signals in normal cell lines than that in cancer cells, and the signals of H3K79me2 changed more significantly than H3K36me3 during tumorigenesis." (PMID 37426199, 2023). "The lncRNA HOTAIR was found upregulated in human TC and inversely correlated with miR-1, whose inhibition leads to activation of cyclin D2 (CCND2), a member of the cyclin family, frequently misregulated in human cancer." (PMID 35804851, 2022). "Then, it was demonstrated that JPX increased cyclin D2 (CCND2) expression by competitively interacting with miR-145-5p, thus promoting cell proliferation and migration and contributing to cancer progression." (PMID 35054794, 2022). "Among these genes, we focused on CCND2 and CCND3, which were cell cycle regulators and involved in promoting cell proliferation in cancer cells." (PMID 35265169, 2022). "Among the validated gene targets of both miR-194-5p and miR-374a-5p, we also found CCND2, AXIN2, and BMPR2, regulated by the Hippo signaling pathway, involved in stemness and cancer biology." (PMID 34828332, 2021). "Similarly, in the present study, we demonstrated that CCND2 AS1 expression was upregulated by treatment with the demethylation reagent 5′-Aza in cervical cell lines, suggesting that CCND2 AS1 transcription might also be regulated via promoter methylation/demethylation in this type of cancer." (PMID 32607313, 2020). "Knockdown of FBXL8 in BRCA cells resulted in the accumulation of CCND2 and IRF5, concomitant with cancer suppression." (PMID 32784654, 2020). "Genes that are commonly hypermethylated across the four cancers in the Hippo and Wnt pathways include APC, CCND2 FZD, TCFs and WNTS (2, 3, 3A, 5A, 7A, and 9B), suggesting a link between the two pathways during oncogenesis." (PMID 33143142, 2020).
cancer (continued). "Further investigations of CCND2 AS1 expression and function in additional cancers will be necessary to confirm these observations." (PMID 32607313, 2020). "Altogether, our computer modeling prediction and retrospective studies highlight the potential role of FBXL8 E3 ligase in specific degradation of CCND2 and IRF5 proteins as cancer progresses." (PMID 32784654, 2020). "CCND1 (FC 2.59), BCL2L1 (FC 2.25), MYC (FC 3.70), along with CCND2 (FC 1.60) and SOCS7 (FC 1.51), are all located downstream of STAT activation and were upregulated in carcinoma tissue." (PMID 30603058, 2018). "CDKN2A has length as the dominant determinant over amplitude in 6/8 cancers, while all 16 cancer types with MYC, CCND2, TERT, or AKT3 amplifications show low AUCs for both parameters." (PMID 26787600, 2016). "Previous studies showed that miR-34a targets the oncogenes CDK4, CDK6, CCND1, MET, and BCL2, whereas miR-497 targets the oncogenes CCND2 and BCL2 in various types of cancer." (PMID 25909221, 2015). "Although our limited data suggests that CCND2 is a potential tumor suppressor gene (TSG) in UCC, the role of CCND2 in human cancer is controversial." (PMID 24980822, 2014). "In the present study, we found that CCND2 is significantly more methylated in recurrent than in non-recurrent LGPUCC, which indicates a potential similar biological role for CCND2 in NSCLC and LGPUCC, two types of cancers related to smoking." (PMID 24980822, 2014). "Stepwise Cox regression modelling suggested that the methylation of genes HSPB1, CCND2 and DPYS contributed objective prognostic information to Gleason score and PSA with respect to cancer-related death during follow-up (p = 0.006)." (PMID 25193387, 2014). "Accordingly, overexpression of CCND2, E2F1 and E2F2 were reported in various cancer types, including OS." (PMID 25174983, 2014). "In cancer cells, SFN modulated promoter methylation and expression of cyclin D2 and hTERT via the inhibition of DNMT." (PMID 24466240, 2014). "Only APC (39%), CCND2 (21%), CDH1 (7%), and RARB (4%) were hypermethylated in >2% of these cancer-free subjects." (PMID 21577262, 2011). "We examined the hypermethylation status of a panel of 5 normally unmethylated tumor suppressor or cancer genes: FHIT, FANCF, Cyclin-D2, BRCA2 and RUNX3 in 25 ovarian GCTs and ovarian cell line DNAs using the MSP assay." (PMID 15574200, 2004). "It’s still unclear why CCND2 is absent in cancer, yet cell proliferation related to CCND2 is observed." (PMID 40678058, 2025). "Additionally, LINC01405 upregulation led to the increased cell populations, proliferation, and upregulation of critical cancer‐related genes, including AKT1, AKT3, mTOR, WNT3A, SMAD3, CYCLIN D1, CYCLIN D2, BCL2, and GSK3B." (PMID 38225865, 2024). "Consistent with the effects on the cancer cell growth and survival, knockdown REV-ERBα strongly decreased expression of proteins important for growth, proliferation, and survival including MYC, CDK4, CDK6, CCND2/D3, and BCL2." (PMID 39383000, 2024). "Amplifications of CCND1, CCND2, and CCND3 are frequently observed across multiple cancer types." (PMID 38612902, 2024). "Based on the Cancer Genome Atlas (TCGA) cancer database, we used LASSO regression analysis to identify the six prognostic-related genes with both DDR and EMT functions, including TP63, YWHAZ, BRCA1, CCND2, YWHAG, and HIPK2." (PMID 36673982, 2023). "CCND2 was the only common gene significantly upregulated in NSCLC and CSC‐treated Beas‐2B cell lines, suggesting a role of CCND2 in promoting centrosome clustering to help cancer cells divide and continue generating progeny." (PMID 36621828, 2023). "It has been shown that Nic induces downregulation of CDK2 and CDK4, but not CDK7, cyclin D2 or cyclin H in other cancer types." (PMID 36304150, 2022). "The data from the clinical sample suggested miRNA -93-5p has a negative correlation with CCND2 levels in cancer patients." (PMID 35306579, 2022).
cancer (continued). "Furthermore, alterations in the associated genes (CDK-1, CDK-4, CCNE1, CDKN2A, RBI, NCAPG, AURKA, and CCND2) were determined in five CRC studies (CRC, TCGA, Firehose, CRC, TCGA, Nature, CRC, Pan-Cancer, MSKCC and CPTAC-2)." (PMID 33732631, 2021). "Among cancer‐critical genes (defined in the COSMIC Cancer Gene Census), recurrent high‐level amplifications were found only of ERBB2 in two patients, while EGFR and the cell cycle genes CDK6, CCND2, and CCND3 were amplified in one patient each." (PMID 33325154, 2021). "While FBXL8 promotes cancer growth/metastasis, CCND2 and IRF5 suppress cancer progression." (PMID 32784654, 2020). "CCNB1IP1, CCNC, CCND2, CDK5R2, CDK9, and GAK were upregulated in all three cancer regions." (PMID 33302383, 2020). "Therefore, we conducted this meta‐analysis to explore the prognostic role of CCND2 and CCND3 in multiple human malignant neoplasms." (PMID 30950241, 2019). "To analyze whether such a correlation might exist in human cancers, we downloaded data on PICOT and CCND2 mRNA expression levels in 32 types of human cancers available at the Cancer Genome Atlas (TCGA) dataset." (PMID 31527584, 2019). "Information obtained from the Cancer Genome Atlas (TCGA) database verified the negative correlation between PICOT and CCND2 in eight different human cancer types." (PMID 31527584, 2019). "Since our data demonstrated a negative correlation between PICOT and cyclin D2 mRNA expression levels in selected types of human cancers, we further analyzed the impact of such a correlation on the overall patients’ survival." (PMID 31527584, 2019). "Interestingly, the existence of outliers in different cancer types suggests that additional mechanisms, besides PICOT-induced altered trimethylation of H3K27 at the CCND2 gene promoter, are likely to affect the cell cycle and growth rate of these cells." (PMID 31527584, 2019). "An intestinal immune network for IgA production might provide new markers in enteric DLBCL, such as CCR10, TNFRSF13B, AICDA, and HLA-DOB, as well as genes involved in transcriptional misregulation in cancer (NFKBIZ, FUT8, LMO2, CCND2, BCL2A1, ETV6, and CDK14)." (PMID 29992138, 2018). "From the seven most promising candidates, six (APC, CCND2, FOXA1, PSAT1, RASSF1A and SCGB3A1) confirmed its cancer-specificity, discriminating normal from cancerous tissues, although with variable performance, paralleling previous observations from our team and others." (PMID 30405052, 2018). "The effect of JQ1 on MSCs in our study, as well as on cancer cell lines in the other studies, are in line with the previous studies showing that BRD4 activates the transcription of CCND1 and CCND2, and that their expression is reduced in NIH3T3 cells after knockdown of BRD4." (PMID 26830473, 2016). "Hypermethylation of APC, CCND2, GSTP1, PTGS2 and RARB was highly cancer-specific." (PMID 26086362, 2015). "Hypermethylation of the CCND2, ESR1 and WNT5A loci has been reported in various cancer types." (PMID 24586797, 2014). "While cyclin D1 is frequently dysregulated in cancer and is a marker for disease progression, the involvement of cyclin D2 in cancer is not as well characterized." (PMID 24009521, 2013). "Of those differentially expressed in our study, 14q32 miRNAs having confirmed targets include miR-127 (located within a CpG island and silenced in many cancers) targeting BCL-6, miR-154 targeting CCND2, miR-433 targeting HDAC6, miR-485-3p targeting NF-YB and miR-539 targeting HLCS." (PMID 23717541, 2013).